MPO (myeloperoxidase)
Diseases named in the same sentence as MPO in open-access papers (continued):
Sharing a sentence is not in itself a finding about the gene and the disease.
acute kidney injury (33 papers, 2001 to 2025). Sudden and sustained deterioration of the kidney function characterized by decreased glomerular filtration rate, increased serum creatinine or oliguria. "The increased expression of NLRP3 in patients with severe AP also causes elevated kidney MPO levels and triggers a cytokine cascade, contributing to renal damage and acute kidney injury (AKI) in severe AP models." (PMID 39596901, 2024). "One child (case 9) had pauciimmune necrotizing crescentic glomerulonephritis associated with anti-neutrophil cytoplasmic antibodies (ANCAs) against myeloperoxidase, and presented with severe acute kidney injury, already with extensive chronic kidney damage." (PMID 38123711, 2024). "A “triple positive” disease (anti-GBM, myeloperoxidase (MPO), and proteinase 3 (PR3)) causing an isolated renal failure is even rarer." (PMID 36419545, 2022). "Our case of triple-positive disease is an even rarer cause of isolated renal failure, as it includes anti-GBM, antimyeloperoxidase (MPO), and antiproteinase 3 (PR3)." (PMID 36419545, 2022). "This diagnosis should be considered in any scleroderma patient with positive MPO antibodies and renal failure." (PMID 20827302, 2010). "This patient had ILD, acute renal failure, proteinuria, and a high titer of MPO-ANCA positivity." (PMID 40500569, 2025). "However, one of them died of renal failure after 12 years of treatment, probably as a result of MPO-ANCA-related nephritis." (PMID 36789128, 2023). "Patient A had complications of stage 3 acute kidney injury on presentation as well as high dual anti-MPO and anti-GBM antibody levels requiring more aggressive treatment, which may have blunted the vaccine response." (PMID 37514968, 2023). "In addition, we discussed the role of modified lipoprotein particles under the influence of prooxidant MPO intermediates in the development of endothelial changes and cardiovascular complications in renal failure." (PMID 27127544, 2016). "Despite progress made in understanding the complex mechanisms of MPO and MPO-derived reactive intermediates activities, further research in order to determine the exact role in the development of oxidative stress and inflammation in renal failure would be certainly justified." (PMID 27127544, 2016). "HSP increased Nrf2 signalling, SIRT6, NQO1, HO-1 expression, down-regulated SCr, blood urea nitrogen (BUN), MDA, MPO, GSH, SOD, NOX4 expression level, thereby relieving cisplatin-induced acute kidney injury." (PMID 35128104, 2022). "In addition, our patient presented with acute kidney injury (AKI), proteinuria, and antineutrophil cytoplasmic antibodies (ANCAs) positive for MPO, findings that were related to MPA." (PMID 39963201, 2025). "Acute kidney injury was seen in two patients with combined positivity for anti-myeloperoxidase and anti-proteinase 3 antibodies, though neither patient progressed to the point of requiring renal replacement therapy." (PMID 26635879, 2015). "Moreover, there was a report that a mother with positive MPO-ANCA gave birth to her neonate who manifested fetal pulmonary hemorrhage and renal failure, and supporting MPO-ANCA from the mother may be able to result in MAP (mean airway pressure) damage in the newborn." (PMID 36210838, 2022). "Among cases with MPO-ANCA-positive RPGN, there tended to be fewer CKD G stage 5 cases than in the nationwide questionnaire survey, suggesting that some cases of severe renal failure were not registered." (PMID 40146365, 2025). "Among the 15 MPO-ANCA positive patients, 13 (86.7%) showed acute kidney injury and received kidney replacement therapy (KRT) at presentation, while the percentage was 68.9% (42/61) in patients without MPO-ANCA positive." (PMID 36408940, 2022). "Our case isunique in that the patient’s renal failure was due to MM and not AAV despitepositive MPO and PR-3 ANCA." (PMID 31043084, 2019).
gastric ulcer (33 papers, 2012 to 2026). An ulcerated lesion in the mucosal surface of the stomach. "Alendronate causes oxidative gastric damage by increasing myeloperoxidase activity and lipid peroxidation, which cause the formation of gastric ulcers and impair gastric ulcer healing." (PMID 34201202, 2021). "Previous studies have found that as a crucial indicator of neutrophil infiltration, an increase in MPO level was often observed in the gastric ulcer caused by ethanol." (PMID 32325708, 2020). "Administration of rHMGB1 at a dose of either 100 μg/kg or 1000 μg/kg significantly suppressed gastric ulcer healing, which was associated with increased MPO activity and TNFα mRNA expression in ulcerated tissues." (PMID 24244627, 2013). "The impaired healing of gastric ulcer in diabetic rats was associated with suppressed tissue expression endothelial cell markers (i.e. eNOS and peNOS), enhanced pro-inflammatory reactions (i.e. IL-1β, IL-6 and myeloperoxidase activity) and reduced regenerative activity (i.e. MMP-2, IL-10 and cAMP)." (PMID 29095895, 2017). "After 14 days of treatment, we found that FPH ameliorated gastric mucosal injury, decreased the activity of MPO, decreased the expression levels of cytokines, and increased the activity of antioxidant enzymes in the ethanol-induced gastric ulcer model." (PMID 36552666, 2022). "The creation of stomach lesions is linked to ethanol-induced neutrophil infiltration, a crucial step in the development of gastric ulcers, and can be measured by myeloperoxidase (MPO) activity." (PMID 36544526, 2022). "In this study, we demonstrated that exogenous HMGB1 delays gastric ulcer healing, while inducing TNFα expression and MPO activity." (PMID 24244627, 2013). "The MPO assay is widely used as an index of neutrophil infiltration in various gastric ulcer models." (PMID 23228052, 2012). "Gastric ulcer rats had increased MPO activity in the stomach by 204%." (PMID 38911236, 2024). "The activity of MPO is related to the inflammatory process in gastric ulcers." (PMID 38435992, 2024). "In addition, the supplementation of OLE or OLR to ethanol-induced gastric ulcer tats inhibits inflammation at the level of gastric tissues, observed by an important inhibition of MPO activity and TNFα and IL6 rates and improvement of NO rate." (PMID 38911236, 2024). "The other investigation showed that montelukast is capable of decreasing the MPO function in neutrophils, prevention of LTs synthesis, and stomach mucosal permeability to involved ions and local increment in the PGs production after gastric ulcers induced by indomethacin." (PMID 33489039, 2020). "In a rat model of gastric ulceration, PSUT and PSUM significantly reduced inflammation and lymphocytic infiltration and lowered the activities of 5-lipoxygenase and myeloperoxidase." (PMID 41771801, 2026). "For example, in mice with gastric ulcers, ruscogenin significantly decreased the levels of TNF-α, IL-6, IL-8, lipid peroxidation (LPO), and myeloperoxidase (MPO) while enhancing the activities of glutathione (GSH) and glutathione peroxidase (GSH-Px)." (PMID 41302473, 2025). "TNFα overexpression and excessive neutrophil infiltration are important factors in delayed healing of gastric ulcers, while exogenous HMGB1 induces TNFα expression and Myeloperoxidase (MPO) activity." (PMID 39008169, 2024). "Pretreatment with C. citrinus and OME-ameliorated gastric ulceration damage induced by IND, via anti-inflammatory mechanisms, by decreasing MPO, COX-2, and 5-LOX activities and inflammatory cytokines (TNF-α and IL-6)." (PMID 38435992, 2024). "Cheng, Lu & Yen (2017) reported that gastric ulcers have various processes such as the activation of phospholipase A, COX-2, myeloperoxidase (MPO), and pro-inflammatory cytokines (TNF-α, IL-6, and leptin)." (PMID 38435992, 2024). "The results indicated that WOPs can protect against indomethacin-related gastric ulcers by increasing the synthesis of PGE2 and reducing the MPO and NO levels." (PMID 37049515, 2023).
gastric ulcer (continued). "Gastric wall nonprotein sulfhydryl (NPSH) group content, myeloperoxidase (MPO) activity, and malondialdehyde (MDA) content were evaluated in ethanol-induced the gastric ulcer model." (PMID 37064952, 2023). "In the in vivo experiments, Aucklandiae Radix notably relieved the gastric ulcer by reducing the levels of tumor necrosis factor (TNF)-α, interleukin (IL)-1β, and myeloperoxidase (MPO) while improving the gastric histopathological features." (PMID 37109624, 2023). "Our experiments showed that the prevention of gastric ulcers induced by RWIS in rats was mainly exerted by increasing GSH-Px and decreasing MPO and MDA." (PMID 33628315, 2021). "Our study indicated a marked increase in the activity of MPO in the mice stomach after the administration of ethanol, however, pretreatment with LCA prior to ethanol induced gastric ulcer significantly decreased the levels of MPO activity in the stomach." (PMID 26694339, 2015). "Additionally, in gastric ulcers induced by ethanol, menthofuran completely restored MDA levels and MPO activity, and partly NPSH, of the rat gastric wall." (PMID 37064952, 2023). "It reduced gastric ulcers (GU) by suppressing ethanol-induced nuclear factor-κB (NF-κB) activity and decreasing the levels of nitric oxide (NO), malondialdehyde (MDA), tumor necrosis factor-α (TNF-α), interleukin-6 (IL-6), interleukin-8 (IL-8), and myeloperoxidase (MPO)." (PMID 34769415, 2021).
cystic fibrosis (32 papers, 1995 to 2025). Autosomal recessive disorder caused by pathogenic variants in the CFTR gene (cystic fibrosis transmembrane conductance regulator), which encodes a chloride and bicarbonate channel expressed in epithelial cells, and follow the diagnosis criteria. "In humans, elevated levels of MPO in cystic fibrosis sputum have been associated with the severity of lung disease." (PMID 33467081, 2021). "Human cystic fibrosis and atrial fibrosis, as well as liver fibrosis in a mice model, have been associated with MPO-induced tissue injury." (PMID 33467081, 2021). "Myeloperoxidase is the major peroxidase enzyme in neutrophil granules and implicated in contributing to inflammatory lung damage in cystic fibrosis." (PMID 28135312, 2017). "Additionally, MPO was linked to fibrotic conditions, such as fibrosis induced by nonalcoholic steatohepatitis or lung cystic fibrosis." (PMID 36835008, 2023). "The severity of pulmonary lesions in patients with cystic fibrosis is related to the levels of MPO in the sputum." (PMID 36835008, 2023). "The MPO in cystic fibrosis lung fluid (sputum) generates hypochlorous acid (HOCl) resulting in toxic peroxidase activity and is likely due to neutrophil degranulation, cell death, or neutrophil extracellular trap (NET) formation." (PMID 35222367, 2022). "In the cystic fibrosis airways, MPO acts as a phagocyte-derived NO oxidase that diminishes NO bioavailability and, consequently, its immune protective (anti-bacterial and anti-viral) and anti-inflammatory properties." (PMID 36230630, 2022). "The inflammatory response and the concentration of MPO in bronchi of cystic fibrosis patients with infections were disproportionate." (PMID 35019674, 2022). "Recent studies have shown that ABAH reduced MPO-dependent mice hepatocyte death, decreased the activity of MPO in acute stroke in mice, and inhibited MPO in cystic fibrosis sputum in humans." (PMID 33467081, 2021). "Cystic fibrosis patients’ sputum contains high concentrations of MPO and human neutrophil elastase (HNE), and these levels correlate with the severity of the lung disease." (PMID 29669993, 2018). "Using TMB as the oxidizing substrate, PIC1 inhibited myeloperoxidase activity in cystic fibrosis sputum soluble fractions by an average of a 3.4-fold decrease (P = 0.02)." (PMID 28135312, 2017). "Cystic fibrosis sputum constituents include DNA, NE, MPO, and other neutrophil proteins, as it has been shown that bronchoalveolar lavage fluid (BAL) from CF infants presented high concentrations of DNA, which correlated with neutrophil numbers in BAL." (PMID 27574522, 2016). "Also, the inhibition of MPO reduced morbidity and oxidative stress in mice with cystic-fibrosis-like lung inflammation." (PMID 38275657, 2024). "The correlation of active MPO with the severity of cystic fibrosis has also been proven." (PMID 37513924, 2023). "Free myeloperoxidase is present in cystic fibrosis lung fluid and generates hypochlorous acid." (PMID 28135312, 2017). "Indeed Van der vliet et. al., have shown that in cystic fibrosis, MPO is the chief mediator of oxidative damage within the respiratory tract." (PMID 22132121, 2011). "The over-expression of MPO by macrophages and non-myeloid cells is also an aetiology associated with cystic fibrosis and hepatic fibrosis." (PMID 19912645, 2009). "MPO is present in the lung fluid of cystic fibrosis patients likely as the result of neutrophil degranulation or cell death." (PMID 28135312, 2017). "Furthermore, in vitro studies have shown that the induction of metalloproteinases by IL-17, which can lead to the characteristic edema formation in the nasal polyps of patients with cystic fibrosis, is characterized by abundant neutrophils and increased concentrations of IL-8 and MPO." (PMID 26594227, 2015).
cystic fibrosis (continued). "Cystic fibrosis is a debilitating lung disease due to mutations in the cystic fibrosis transmembrane conductance regulator protein (CFTR) and is associated with chronic infections resulting in elevated myeloperoxidase activity and generation of hypochlorous acid (HOCl)." (PMID 20799947, 2010). "MPO released from neutrophils contributes to inflammatory lung damage in cystic fibrosis patients." (PMID 35222367, 2022). "Since cystic fibrosis is associated with enhanced formation of MPO-generated oxidants, it would be interesting to know whether MPO is one of the yet unidentified modulatory factors intrinsic to CF." (PMID 23508943, 2013). "In nasal inflammatory diseases, such as cystic fibrosis, both LPO and myeloperoxidase (MPO), another mammalian peroxidase secreted by neutrophils, are known to co-localize." (PMID 22132121, 2011). "Our current study’s findings demonstrate that RLS-0071 can inhibit MPO oxidative activity and dose-dependently reduce NET formation in vivo triggered by a variety of potent inflammatory stimuli that contribute to the pathogenesis of cystic fibrosis." (PMID 34242348, 2021). "In the present study, we evaluated serum biomarkers in children/adolescents with cystic fibrosis and found that the interleukin-1β and myeloperoxidase levels were significantly higher in the cystic fibrosis group than in the group without cystic fibrosis." (PMID 29267535, 2018). "At the baseline of the study, higher median interleukin-1β and myeloperoxidase values were found in the cystic fibrosis group than in the group without cystic fibrosis (P < 0.001)." (PMID 29267535, 2018). "I order to study the time-course of myeloperoxidase (MPO) and eosinophil cationic protein (ECP) as parameters for monitoring inflammation in cystic fibrosis, we investigated ten patients during both a 14-day intravenous antibiotic treatment and a corresponding self control." (PMID 18475652, 1995).
injury (31 papers, 2008 to 2025). Damage inflicted on the body as the direct or indirect result of an external force, with or without disruption of structural continuity. "Previous studies have shown that elevated MPO-DNA levels in the plasma are associated with transfusion-related acute lung injury, ANCA-associated small vessel vasculitis, acute liver failure, severe coronary atherosclerosis, and thrombotic microangiopathies related to their pathogenic mechanisms." (PMID 39457503, 2024). "These cells induce the hepatic production of IL-10 and TNF-α, which also increases in the setting of renal ischemia–reperfusion injury and is responsible for a 10-fold increase in myeloperoxidase (MPO) activity in the liver." (PMID 40722691, 2025). "In this study, Fludarabine significantly reduced neutrophil counts and MPO activity in LPS-induced acute lung injury, suggesting its role in attenuating neutrophil activation and inflammation." (PMID 40336064, 2025). "Oral administration of stearic acid (SA) displayed protective effects in cholestasis-induced liver injury in rats, decreasing the accumulation of leukocytes, MPO activity, activation of NF-κB, and production of transforming growth factor-beta 1 (TGF-β1)." (PMID 39339251, 2024). "It has anti-inflammatory, antioxidant, and hepatoprotective properties, mainly by inhibiting stress signal transduction as it suppresses Cyclooxygenase-2 (COX-2), nitric oxide synthase, and myeloperoxidase (MPO) in CCl4-induced liver injury." (PMID 36877411, 2023). "CAPE administration in mice with traumatic brain injury can inhibit the formation of myeloperoxidase as a marker of accumulated neutrophils, that accumulate after traumatic brain injury thereby preventing brain damage in traumatic brain injury." (PMID 32419943, 2020). "•CAPE administration in mice with traumatic brain injury can inhibit the formation of myeloperoxidase as a marker of accumulated neutrophils." (PMID 32419943, 2020). "The results of this study show a significant decrease of MPO levels in blood serum after traumatic brain injury that receives CAPE." (PMID 32419943, 2020). "Our findings were consistent with those of previous reports where treatment with Ac2-26 in rats significantly reduced PMN recruitment and MPO activity in IR-injured hearts, intestines, and LPS-induced lung injuries." (PMID 28809781, 2017). "Similarly, total flavonoids from Inula japonica (TFIJ) significantly inhibited lipid peroxidation markers, such as malondialdehyde (MDA) and myeloperoxidase (MPO), in an LPS-induced acute lung injury model." (PMID 40864793, 2025). "Interestingly, rodents rendered obese with HFD exhibit lower lung myeloperoxidase activity and reduced Tnf‐α and Mcp‐1 expression in lung neutrophils after acute lung injury (ALI) induced by LPS." (PMID 41019181, 2025). "Furthermore, MPO suppresses neutrophil apoptosis and delays the spontaneous resolution of inflammation, resulting in the perpetuation of carrageenan-induced acute lung injury in mice." (PMID 36421487, 2022). "This increase in MPO activity also occurs after 24 and 48 h post traumatic brain injury." (PMID 32419943, 2020). "Interestingly, PTX was shown to decrease lung MPO activity and NF-kappaB activation, in the model of LPS-induced acute lung injury in rats." (PMID 21167055, 2010). "In a mouse model of traumatic brain injury, a single dose of telmisartan given 6 h after injury caused reduced perilesional staining for CD68, ionized calcium binding adaptor molecule 1 (Iba-1), and myeloperoxidase (MPO) at 72 h, while a similar treatment 24 h after injury had no such effect." (PMID 27562117, 2016). "It has been reported that thymol could significantly mitigate LPS-induced rise of MPO and MDA levels as well as the NF-κB expression in an acute lung injury mice model." (PMID 31763213, 2019).
injury (continued). "In a model of acute lung injury, genistein has been shown to suppress cytokine-inducible neutrophil chemoattractant (CINC) and matrix metalloproteinase-9 (MMP-9) production leading to the inhibition of neutrophil infiltration and activation, and the reduction of MPO activity." (PMID 35927726, 2022).